STK4 (serine/threonine kinase 4)
Diseases named in the same sentence as STK4 in open-access papers (continued):
Sharing a sentence is not in itself a finding about the gene and the disease.
tumor (continued). "Studies have revealed the expression of STK4 in immune and tumor cells." (PMID 37893233, 2023). "Moreover, among the 66 potential mRNA targets of miR‐28‐5p, STK4 which was a known negative regulator of Wnt signaling pathway and a tumor suppressor in NSCLC,22, 30 attracted our attentions." (PMID 37081781, 2023). "Moreover, we employed siRNA to silence the STK4 expression in HepG2 to investigate the anti-tumor effect of SS-b2 in vitro." (PMID 37893233, 2023). "Previous studies have reported that STK4 has tumor‐suppressive ability." (PMID 32741119, 2020). "Furthermore, STK4 knockdown enhanced sphere formation and metastasis in vitro and promoted tumor development in vivo." (PMID 32741119, 2020). "STK4 acts as a tumor suppressor, and its overexpression inhibits tumor growth." (PMID 32741119, 2020). "RAS bound with RASSF5, activate MST1/235,44 to form STK3/MST2 and STK4/MST1 complexes in the hippo signaling pathway that plays a crucial role in tumor suppression by limiting proliferation and stimulating apoptosis where SAV1, MOB1A/B act as effector molecules." (PMID 32884013, 2020). "STK4 silencing was observed to promote the proliferation ability of TC cells, inhibit the apoptosis and autophagy abilities, as well as enhance the tumorigenicity and tumour growth." (PMID 31657132, 2020). "Mice were fed with Dox in drinking water to induce STK4 expression in tumor cells." (PMID 28880957, 2017). "Surprisingly, we found that STK4 may have tumor-promoting effects in our study." (PMID 37870765, 2023). "Among these were genes with putative tumor suppressor function in different cancer types including FOXP1, STK4,ATM, and others." (PMID 38464090, 2024). "Serine/threonine protein kinase 4 (STK4), a pivotal regulator of the Hippo–YAP pathway, plays an important role in suppressing tumor cell growth." (PMID 37893233, 2023). "Meanwhile, mechanistic experimentation demonstrated that circRNA_0057209 promoted STK4 expression by sponging miR-183, while STK4 enhanced YAP phosphorylation to mediate the Hippo pathway, thereby suppressing tumor progression." (PMID 35308166, 2022). "MiR-18a directly targets the STK4 3′-UTR, a tumor suppressor gene that correlates with the Hippo pathway involved in the hyperproliferative state of the tumor cells." (PMID 34957212, 2021). "miR-18a acts as an oncomir: it targets the serine/threonine kinase 4 (STK4) 3’ untranslated region, inducing its downregulation and promoting tumor survival." (PMID 32268584, 2020). "The genes most frequently showing CNGs in HAS tumour tissues were TOP1 (50.0%), STK4 (45.5%), CDKN1B (40.9%), H3F3A (36.4%), MYC (22.7%), CCNE1 (22.7%), NFKBIA (22.7%), VEGFA (18.2%), CCND3 (13.6%), and E2F1 (13.6%)." (PMID 30989433, 2019). "Moreover, RASSF6 directly activates the Hippo pathway by enhancing the phosphorylation of STK4/3 and LATS1/2 kinases, thereby reinforcing its role as a critical upstream activator of Hippo tumor-suppressive signaling." (PMID 41153630, 2025). "We also found that putative tumor suppressors, such as FOXP1, STK4, and ATM were frequently hypermethylated and silenced whereas oncogenes, such as UHRF1, MPZL1, CDK14, RACGAP1, and RAB13, were hypomethylated and overexpressed suggesting that DNA methylation changes contribute to PTCL development." (PMID 38464090, 2024). "Mammalian STE20-like kinase 1 (MST1/STK4/KRS2) is a highly conservative serine/threonine kinase, as well as a core member of the Hippo signaling pathway, which plays a role in regulating cell cycle, promoting apoptosis and inhibiting tumor growth." (PMID 37870765, 2023).
tumor (continued). "Also, miR-18a-5p showed to attenuate the expression of the pro-apoptotic protein serine/threonine kinase 4 (STK4), consequently resulting in an increased AKT phosphorylation and enhanced tumor cell survival." (PMID 36608541, 2023). "The results indicated that STK4 highly expressed in nontumor sections, but low or no expression of STK4 was found in the benign or tumor tissues (P < 0.001)." (PMID 32741119, 2020). "STK4 was highly expressed in the benign section but low or no expression of STK4 in tumor and metastatic tissues." (PMID 32741119, 2020). "The expression levels of EGF-EGFR-RAS signaling marker genes EGF, EGFR, HRAS, RASSF1 and STK4 in the HLX22 and HLX02 combination-treated cells decreased, suggesting that HLX22 in combination with HLX02 inhibited EGF-EGFR-RAS signaling to suppress tumor proliferation, survival, and invasion." (PMID 38982548, 2024). "Moreover, STK4 and STK3 have been established as tumour suppressor proteins." (PMID 32555725, 2020). "Additionally, STK4 and STK38 are critical serine/threonine kinases regulating the cell cycle and apoptosis; they also exhibited an upregulation trend in the PTX+3-MA group, suggesting that 3-MA may induce tumor cell cycle arrest and apoptosis, thereby enhancing drug efficacy." (PMID 40649969, 2025).
cancer (21 papers, 2010 to 2024). A tumor composed of atypical neoplastic, often pleomorphic cells that invade other tissues. "The isoform switch I identified in STK4 results in the central part of the Pkinase domain, including the active sites, being removed from the cancer isoform." (PMID 37745975, 2023). "A prominent example is the isoform switch in the STK4 gene (frequently called MST1) found in three cancer types: thyroid, kidney and colorectal." (PMID 37745975, 2023). "Initially, we compared the expression levels of STK4 in cancer and normal tissues using the TIMER database." (PMID 37870765, 2023). "It has been reported that STK4 plays important roles in tumorigenesis in multiple cancers including prostate cancer, breast cancer, and hepatocellular carcinoma." (PMID 37870765, 2023). "As the canonical activator of the Hippo pathway STK4 serves as a negative regulator of tumourigenesis, consequently its expression is down-regulated in several cancers." (PMID 32555725, 2020). "In summary, we identified several DE genes and molecular pathways that are responded to the targeted STK4 expression and these pathways are known to be biologically and clinically relevant to human cancer including PC." (PMID 28880957, 2017). "Dysregulation of MST1/STK4, a key kinase component of the Hippo-YAP pathway, is linked to the etiology of many cancers with poor prognosis." (PMID 28880957, 2017). "We found that STK4 was highly expressed in various types of cancer, including ccRCC." (PMID 37870765, 2023). "We speculated that the different roles of STK4 toward tumors are related to the heterogeneity of cancer." (PMID 37870765, 2023). "Thus, we propose a mechanism how STK4 regulates β‐catenin degradation between normal cells and cancer cells." (PMID 32741119, 2020). "This strongly suggests a cancer predisposition mechanism of STK4 mutations independent of EBV infections." (PMID 30386345, 2018). "However, how STK4 restricts the emergence of aggressive cancer remains elusive." (PMID 28880957, 2017). "Reintroduction of STK4 or STK3, into HPV+ cancer cells inhibited their proliferation, migration and invasion." (PMID 32555725, 2020). "Given that we observed increased Hippo pathway signalling in all cell lines overexpressing STK4, our results suggest that HPV+ cancer cells are particularly sensitive to re-activation of this pathway." (PMID 32555725, 2020). "In addition, the four overlapping target genes of miR-7977 (CCL22, STK4, HSPA1B, and ACTR2) in all three databases were reported to have a key role in cancer formation and metastasis." (PMID 32328453, 2020).
infection (4 papers, 2016 to 2023). The state of being infected such as from the introduction of a foreign agent such as serum, vaccine, antigenic substance or organism. "Further, knock down of MST1/2 by Stk4/Stk3 siRNA in RAW264.7 and THP1 macrophages also led to a significant loss in infection-driven IRF3 activation." (PMID 27883091, 2016). "Consequently, the infection induced apoptosis in cholangiocytes via the CD40 molecule (CD40), caspase recruitment domain family member 8 (CARD8), and serine/threonine kinase 4 (STK4)." (PMID 37958904, 2023).
hematologic malignancies (2 papers, 2021). "Reduction of the kinase STK4 restores YAP1 and stimulates programmed cell death, giving justification for the identification of new STK4 inhibitors for clinical use in the treatment of hematologic malignancies." (PMID 33924049, 2021). "However, it should be noted that the Hippo kinase STK4, also identified as a SYK target in DG75 cells, and YAP1, are involved in hematologic malignancies." (PMID 33670716, 2021).
Heart disease (1 paper, 2024). "Heart disease occurs in a small percentage (6/33) of patients and EV was observed in five of the 33 STK4-deficient patients." (PMID 39110273, 2024).
STK4 also shares sentences with these, for which no sentence is quoted: epidermodysplasia verruciformis (4 papers); acute lymphoblastic leukemia (2); genetic disorder (2); T-cell immunodeficiency (2); adenocarcinoma (1); aortic aneurysm (1); Aortic dissection (1); asthma (1); ataxia telangiectasia (1); atherosclerosis (1); autoimmune enteropathy (1); autoimmune hepatitis (1); autoimmune lymphoproliferative syndrome (1); autoimmune thyroiditis (1); Autosomal recessive hyper-IgE syndrome (1); bacterial infections (1); bipolar disorder (1); bladder cancer (1); Burkitt lymphoma (1); cardiovascular diseases (1); cerebrovascular diseases (1); cervical intraepithelial neoplasia (1); Clouston syndrome (1); depression (1); diabetes (1); diphtheria (1); Dyskinesia (1); eczema (1); Failure to thrive (1); follicular lymphoma (1).
A further 25 diseases each share a sentence with STK4 in 1 paper.